GLIS2 (GLIS family zinc finger 2)
Diseases named in the same sentence as GLIS2 in open-access papers (continued):
Sharing a sentence is not in itself a finding about the gene and the disease.
cyst (3 papers, 2013 to 2024). A sac-like closed membranous structure that may be empty or contain fluid or amorphous material. "Inactivation of either polycystin results in upregulation of Glis2 in vivo and in vitro while genetic interventions that suppress cyst growth in vivo, including mutation of several cilia-related genes, similarly suppress increased expression of Glis2 in vitro." (PMID 38693102, 2024). "We found that Glis2 transcript and protein expression changes in primary kidney cell cultures are an in vitro surrogate for in vivo gene expression changes associated with polycystin-dependent cyst formation." (PMID 38693102, 2024). "Furthermore, pharmacological targeting of Glis2 using antisense oligonucleotides suppressed cyst formation and associated secondary changes in the mouse kidney." (PMID 38693102, 2024). "To investigate whether Glis2 has a phenotypic effect in ADPKD, we used a series of mouse allele combinations to determine whether inactivation of Glis2 affected polycystin-dependent cyst progression." (PMID 38693102, 2024). "Interestingly, Glis2 inactivation suppresses cyst formation due to loss of cilia in an early onset model of kidney selective inactivation of Kif3a54." (PMID 38693102, 2024). "We found that an ASO mediating degradation of Glis2 mRNA was effective in reducing polycystic kidney disease severity and attendant tissue level changes including cyst cell proliferation and inflammatory and pro-fibrotic changes in the kidney." (PMID 38693102, 2024). "In aggregate, these data confirm the strong “CDCA pattern” correlation between Glis2 protein nuclear expression and propensity for cyst formation in vivo." (PMID 38693102, 2024). "Fourth, it establishes Glis2 as a functional target of CDCA cyst-promoting activity following polycystin inactivation." (PMID 38693102, 2024). "Glis2 and PC2 protein expression in Pkd1;Tulp3 double knockout cells remained unchanged from non-knockout controls further supporting the strict correlation of Glis2 levels in vitro with polycystin-dependent cyst forming potential in vivo." (PMID 38693102, 2024). "Glis2 transcript and nuclear protein expression is an in vitro molecular readout that is directly correlated with genetic factors that determine in vivo cyst formation." (PMID 38693102, 2024). "Inactivation of Glis2 in early onset and adult mouse models of Pkd1 and Pkd2 resulted in suppression of cyst formation." (PMID 38693102, 2024). "In vitro changes in Glis2 expression mirror the polycystin- and cilia-dependent changes observed in kidney tissue, validating Glis2 as a cell culture-based indicator of polycystin function related to cyst formation." (PMID 38693102, 2024). "Glis2 transcript and protein expression changes in primary cells are an in vitro surrogate indicator of in vivo cyst forming potential resulting from polycystin inactivation." (PMID 38693102, 2024). "Since Glis2 is a transcription factor, it is reasonable to hypothesize that its effects on cyst growth are related to its transcriptional targets." (PMID 38693102, 2024). "Given that our Glis2 dual genetic inactivation data was effective in reducing cysts in the proximal and distal nephron, we expect that compounds able to achieve Glis2 inhibition along the entire nephron would likewise be effective in suppressing cyst growth along the entire nephron." (PMID 38693102, 2024). "While the cadence and mechanisms of cyst formation due to cilia inactivation differ from polycystic kidney disease resulting from inactivation of Pkd1 or Pkd219, this observation does raise the intriguing possibility that Glis2 may be a common downstream effector for both mechanisms." (PMID 38693102, 2024). "We used the Pkd2WS25/− mice which develop cysts following sporadic random second hit events akin to the human disease to extend validation that Glis2 inactivation suppresses cyst formation in non-Cre dependent models." (PMID 38693102, 2024).
cyst (continued). "Absence of Glis2 resulted in significant protection from cyst growth following Pkd1 inactivation as indicated by significant improvements in kidney-to-body weight ratio, cystic index and BUN levels." (PMID 38693102, 2024).
cystic kidneys (3 papers, 2013 to 2024). "The presence of increased interstitial macrophages in control-ASO treated cystic kidneys was significantly reduced following Glis2-ASO treatment." (PMID 38693102, 2024). "In keeping with these observations, control-ASO treated cystic kidneys showed elevated levels of the TNF-α and cleaved caspase-1; both were significantly reduced in mice treated with Glis2-ASO." (PMID 38693102, 2024). "Glis2-ASO treated Pkd1fl/fl; UBCCre-ERT2 mice showed similar presence of sporadic SA-β-gal cell staining that was qualitatively reduced compared to untreated cystic kidneys indicating that Glis2-ASO did not result in increased lysosomal activity as detected by SA-β-gal staining." (PMID 38693102, 2024).
diabetic nephropathy (3 papers, 2023 to 2024). "Crucially, the authors demonstrated that inducing lncRNA Glis2 overexpression in diabetic mice attenuated podocyte apoptosis and pathological changes associated with diabetic nephropathy, including podocyte foot process effacement and glomerular basement membrane thickening." (PMID 39125612, 2024). "Long noncoding RNA (lncRNA) Glis2 was found to inhibit the apoptosis of mouse podocytes in an in vitro model of diabetic nephropathy by ameliorating changes in mitochondrial function and morphology." (PMID 39125612, 2024).
colon cancer (2 papers, 2020 to 2022). "Taken together, we have proved GLIS2 as an oncogene in colon cancer through selectively regulating gene transcription and enhancer activity." (PMID 32483180, 2020). "Furthermore, low expression of GLIS2 is significantly correlated with the overall survival and disease-free survival rates of colon cancer patients." (PMID 32483180, 2020). "Our study showed that GLIS2 is overexpressed in multiple cancers and may be useful for prognosis of colon cancer." (PMID 32483180, 2020). "Big data analysis supports GLIS2 as an oncogene in colon cancer, and perhaps other cancers." (PMID 32483180, 2020).
end-stage renal disease (2 papers, 2015 to 2019). "Studies had linked the function of GLIS2 to autosomal recessive kidney disease and found that GLIS2 was the most common genetic cause of end-stage renal failure." (PMID 31281358, 2019).
gastric cancer (2 papers, 2019 to 2025). A primary or metastatic malignant neoplasm involving the stomach. "In this study, we used the gastric cancer database in TCGA, and significant association was observed between the low expression of GLIS2 and radiosensitivity of patients with gastric cancer." (PMID 31281358, 2019). "Recent study had shown that overexpression of GLIS2 had significant association with chemoresistance of gastric cancer." (PMID 31281358, 2019). "This study elucidates the mechanism by which GLIS Family Zinc Finger 2 (GLIS2) promotes epithelial-mesenchymal transition (EMT) in gastric cancer through biglycan (BGN) activation and Wnt/β-catenin stimulation." (PMID 40936440, 2025). "The relationship between GLIS2 and radiosensitivity of gastric cancer was explored, which provided a new reference for clinical improvement of the therapeutic effect on gastric cancer, and an important clue for basic research on radiosensitivity of gastric cancer." (PMID 31281358, 2019). "The GLIS2 gene might be a potential effective molecular marker of gastric cancer for precise radiotherapy." (PMID 31281358, 2019). "Studies on the association between radiosensitivity of gastric cancer and GLIS2 expression had not been reported before." (PMID 31281358, 2019). "Mechanisms of GLIS2 and radiosensitivity of gastric cancer require further study." (PMID 31281358, 2019). "To verify this hypothesis, we analyzed the relationship between GLIS2 expression and radiotherapy sensitivity based on gastric cancer data from TCGA, to provide references for clinical treatment of gastric cancer." (PMID 31281358, 2019). "However, the association between GLIS2 expression and radiosensitivity of gastric cancer has not been well understood." (PMID 31281358, 2019). "GLIS2 could also regulate the interaction between β-catenin and T-cell factor/Lymphoid enhancer factor (TCF/LEF) to affect the activation of cyclin D1, which may have association with poor tumor differentiation and prognosis in gastric cancer." (PMID 31281358, 2019). "Relationship between the expression of GLIS2 and the sensitivity of radiotherapy for patients suffering from gastric cancer has not been well studied." (PMID 31281358, 2019). "However, in the subgroup analysis, we came to conclude that gastric cancer patients with low expression of GLIS2 were supposed to possess high radiosensitivity, while patients with high expression of GLIS2 gene were not sensitive to radiotherapy." (PMID 31281358, 2019).
glioma (2 papers, 2020 to 2022). A benign or malignant brain and spinal cord tumor that arises from glial cells (astrocytes, oligodendrocytes, ependymal cells). "We would like to investigate if GLIS2 plays roles in glioma progression in our future experiments." (PMID 32293515, 2020).
kidney failure (2 papers, 2021 to 2023). An acute or chronic condition that is characterized by the inability of the kidneys to adequately filter the blood. "Here, we report a case of NPHP associated with early kidney failure caused by a homozygous in-frame deletion of GLIS2 diagnosed using WES." (PMID 34917135, 2021). "Variants in GLIS2 have been previously identified in patients with NPHP (OMIM: 611498) who developed kidney failure in early childhood." (PMID 34917135, 2021). "Here, we identified in GLIS2 an in-frame deletion variant (NM_032,575.3: c.560_574delACCATGTCAACGATT, p.H188_Y192del) in Omani family with NPHP and early onset kidney failure." (PMID 34917135, 2021). "Later, in 2013, a homozygous missense GLIS2 variant (c.523T > C, p.C175R) was identified in a Turkish patient with isolated NPHP who reached kidney failure aged 15 years, as part of a worldwide cohort screen of patients with NPHP-RC." (PMID 34917135, 2021). "The Glis2, a Krüppel-like zinc finger protein, mutant mice had increased cell death and basement membrane thickening in the proximal convoluted tubules, resulting in severe renal atrophy with lymphocytic inflammatory cells infiltration and renal failure." (PMID 37033211, 2023). "Therefore, this study has not only broadened the spectrum of variants within GLIS2, but also extended the molecular pathogenesis spectrum of kidney disease in Oman and allowed the confirmation of the clinical diagnosis of NPHP leading to kidney failure." (PMID 34917135, 2021). "In summary, by employing WES, we detected a novel in-frame deletion (NM_032,575.3: c.560_574delACCATGTCAACGATT, p.H188_Y192del) in GLIS2 in an Omani family with NPHP and kidney failure." (PMID 34917135, 2021).
renal fibrosis (2 papers, 2015 to 2019). A final common manifestation of a wide variety of chronic kidney diseases characterized by glomerulosclerosis and tubulointerstitial fibrosis. "Glis2/NPHP7-deficient mice develop glomerular cystic lesions in combination with severe renal fibrosis and atrophy." (PMID 26083374, 2015).
brain aneurysm (1 paper, 2023). A congenital or acquired aneurysm within the cranium. "Brain aneurysm was observed in eight patients (16%), and the causative genes were PKD1 (missense (n = 2), nonsense (n = 1)), PKD2 (missense (n = 1), splice-site (n = 1)), ZNF423 (missense), GLIS2 (missense) or PKHD1 (missense) or WDR19 (splice-site), and CEP164 (missense)." (PMID 36833371, 2023).
breast tumor (1 paper, 2021). "Claudin-low breast tumors can be segregated from other breast tumor subtypes based on a GLIS2-dependent gene expression signature." (PMID 34705506, 2021). "Collectively, our data showed that primary cilia are assembled in claudin-low breast tumor cells that are enriched in MaTICs, in which they control GLIS2 inactivation to promote the tumorigenic capacity of these cells." (PMID 34705506, 2021). "Subsequently, we found that claudin-low breast tumors are enriched in tumor cells that display an M-like phenotype, assemble primary cilia, and express high levels of GLIS2 target genes, as well as MaSC and Wnt signaling gene programs." (PMID 34705506, 2021).
Cirrhosis (1 paper, 2025). A chronic disorder of the liver in which liver tissue becomes scarred and is partially replaced by regenerative nodules and fibrotic tissue resulting in loss of liver function. "The upregulated genes between cirrhosis and healthy included GSN, COL4A4, CHI3L1, and GLIS2." (PMID 40489530, 2025).
cystic kidney disease (1 paper, 2015). A congenital or acquired kidney disorder characterized by the presence of renal cysts. "Positional cloning revealed that mutations of Glis2/NPHP7 cause type 7 nephronophthisis, an autosomal recessive condition associated with cystic kidney disease and several extra-renal manifestations, including retinitis pigmentosa and cerebellar abnormalities." (PMID 26083374, 2015).
energy metabolic disorders (1 paper, 2022). "Although the depletion of miRNA or target genes both resulted in energy metabolic disorders, whether these metabolic phenotypes under antagomiR treatment were caused by increased expression of SLC2A1 and GLIS2 remains unclear." (PMID 36197879, 2022).
Ewing sarcoma (1 paper, 2025). A small round cell tumor that lacks morphologic, immunohistochemical, and electron microscopic evidence of neuroectodermal differentiation. "Herein, we present a case of isolated extramedullary relapse of CBFA2T3::GLIS2-positive AMKL after a second allogeneic hematopoietic stem cell transplantation (allo-HSCT) in a 3.5-year-old girl who was misdiagnosed with secondary Ewing sarcoma." (PMID 40565358, 2025). "We report a case of a girl with isolated extramedullary CBFA2T3::GLIS2-positive AMKL relapse, which was misdiagnosed as secondary Ewing sarcoma." (PMID 40565358, 2025). "Additional cytogenetic and molecular studies confirmed the presence of the CBFA2T3::GLIS2 fusion, but no Ewing sarcoma-specific EWSR1, FUS and CIC fusion transcripts were found." (PMID 40565358, 2025).
Hyperglycemia (1 paper, 2024). An increased concentration of glucose in the blood. "More accumulation of JC‐1 aggregates and less diffuse JC‐1 monomers were observed in HG + pcDNA3.1‐lncRNA Glis2 group, which indicated that the decrease of ΔΨM caused by hyperglycemia significantly reversed by lncRNA Glis2 overexpression." (PMID 38506068, 2024). "The results indicated that lncRNA Glis2 down‐regulation induced by hyperglycemia might be associated with podocyte apoptosis." (PMID 38506068, 2024). "LncRNA Glis2 overexpression significantly prevented hyperglycemia‐induced changes in mitochondrial morphology." (PMID 38506068, 2024). "The changes in mitochondrial fusion and fission protein induced by hyperglycemia were reversed in HG + pcDNA3.1‐lncRNA Glis2 group." (PMID 38506068, 2024). "Immunofluorescence assay revealed that the down‐regulation of nephrin and podocin induced by hyperglycemia was significantly reversed by transfected with pcDNA3.1‐lncRNA Glis2." (PMID 38506068, 2024). "Flow cytometry showed that lncRNA Glis2 overexpression could alleviate podocyte apoptosis induced by hyperglycemia." (PMID 38506068, 2024).
kidney cancer (1 paper, 2020). Primary or metastatic malignant neoplasm involving the kidney. "A previous study reported that GLIS2 interacts with HDAC3 and regulates gene expression in several kidney cancer cells." (PMID 32483180, 2020).
Kidney Cyst (1 paper, 2024). Abnormal fluid filled sac within the kidney, either acquired or congenital. "Such a hypothesis raises the possibility that transcriptional targets of Glis2 are common elements of kidney cyst formation from diverse genetic causes." (PMID 38693102, 2024).
myeloid leukemia (1 paper, 2021). A clonal proliferation of myeloid cells and their precursors in the bone marrow, peripheral blood, and spleen. "Interestingly, the oncogene in ML23 are known to relate with myeloid leukemia, however, ML21 CLL-like oncogenic analysis revealed Runx1, Evi1, Glis2, and Hoxa9." (PMID 33602907, 2021).
polycystic kidney disease (1 paper, 2024). A usually autosomal dominant and less frequently autosomal recessive genetic disorder characterized by the presence of numerous cysts in the kidneys leading to end-stage renal failure. "We examined the effects of Glis2–∕– null alleles on polycystic kidney disease progression in the Pkd2WS25/− model." (PMID 38693102, 2024). "Second, it identifies Glis2 transcript and protein as an in vivo and in vitro marker of polycystin function specifically related to polycystic kidney disease progression." (PMID 38693102, 2024). "Germline null Glis2 supported persistent relative improvement of polycystic kidney disease with normal kidney-to-body weight ratio and significantly milder cystic index and BUN elevation when compared to Pkd1fl/fl; Pkhd1Cre mice at P49." (PMID 38693102, 2024). "Inactivation of Glis2 suppresses polycystic kidney disease in mouse models of ADPKD, and pharmacological targeting of Glis2 with antisense oligonucleotides slows disease progression." (PMID 38693102, 2024). "Finally, we assessed several additional markers of polycystic kidney disease severity in response to Glis2-ASO treatment in male mice." (PMID 38693102, 2024). "We next sought to evaluate whether Glis2 is a suitable target for preclinical pharmacological intervention to reduce polycystic kidney disease progression." (PMID 38693102, 2024). "Finally, it offers a proof of concept that pharmacological targeting of Glis2 can suppress polycystic kidney disease based on studies in preclinical models." (PMID 38693102, 2024). "To determine whether the changes in Glis2 expression found in Pkd1 models are extensible to other preclinical models of ADPKD, we used a mouse model in which polycystic kidney disease resulting from inactivation of Pkd2 is rapidly reversed by re-expression of Pkd236." (PMID 38693102, 2024).
cancer (12 papers, 2013 to 2025). A tumor composed of atypical neoplastic, often pleomorphic cells that invade other tissues. "Nevertheless, overexpression of human GLIS2 had a negative effect on reprogramming, leading to a decreased number of ESC-like colonies, denoting that GLIS2 gene might be associated with cancers." (PMID 31281358, 2019). "Previous reports showed that GLIS2 is usually involved in the development of cancer as fusion genes." (PMID 32968054, 2020). "The GLIS2 protein is a member of a subfamily of transcription factors that have a great impact on different physiological processes, including cancer." (PMID 31988301, 2020). "The expression of PUMA is negatively correlated with GLIS2 expression in colon and cancer tissues, supporting GLIS2’s role in repressing PUMA expression." (PMID 32483180, 2020). "However, the circRNAs derived from GLIS2 as well as their function in cancer progression are still poorly understood." (PMID 32968054, 2020). "But whether GLIS2 functions in other types of cancers and the underlying molecular mechanisms are not determined." (PMID 32483180, 2020). "Dorsomorphine was found to inhibit the growth of CBFA2T3::GLIS2-positive cells in a dose-dependent manner, while GANT61 interferes with the activity of the fusion protein, leading to cancer cell death." (PMID 41155189, 2025).